TNF (tumor necrosis factor)
Diseases named in the same sentence as TNF in open-access papers (continued):
Sharing a sentence is not in itself a finding about the gene and the disease.
tumor (continued). "Their activation leads to enhanced phagocytosis of tumor fragments and the release of proinflammatory cytokines like TNF-α and IL-1β." (PMID 39372411, 2024). "During the execution of these anti‐tumor immune processes, the levels of certain typical pro‐inflammatory cytokines, namely, IL 2, TNF‐α, IFN‐γ, and granzyme B (GzmB), were analyzed to assess the activation of the immune system." (PMID 38742454, 2024). "Increased ROS production triggers the release of inflammatory factors such as IL-6 and TNF-α, altering the tumor microenvironment, which in turn affects the function of T cells and other immune cells." (PMID 38510247, 2024). "The modified NPs enhance macrophage chemotaxis by upregulating TNF-α expression and induce the accumulation of reactive oxygen species (ROS) after low-dose laser irradiation, resulting in strong anti-tumor effects and improved survival of tumor-bearing mice." (PMID 38169585, 2024). "The use of combined therapies, such as CD40 agonists, tumor necrosis factor and tumor-binding antibodies drives the neutrophil-mediated eradication of cancer." (PMID 39555061, 2024). "Following pFUS, there was a 75% concordance for anti-tumor cytokines and inflammatory markers (including TNFα, IL-1a, IL-1b, IL-17, IL-6, and VCAM-1), indicating a TME shift toward a hot TME." (PMID 38543305, 2024). "The internal tumor-related characteristics (cancer type and stage) and TME define the proapoptotic effects of TNF-α and its ability to inhibit tumor progression." (PMID 38698424, 2024). "Only with simultaneous activation of the Vδ2 T cell TCR, which recognizes phosphoantigens on stressed, infected or tumor cells, did CAR-DAP10 signaling mount a full response with release of IFN-γ, TNF-α, IL-2, IL-4, GzmB and cytotoxicity against tumor cells." (PMID 39061247, 2024). "Prolonged immunotherapy can elevate PD-1 expression in CD4+ and CD8+ T cells, leading to reduced infiltration of these cells into the tumor and decreased levels of activation markers such as IFNγ, TNFα, and granzyme B." (PMID 38927907, 2024). "This differentiation is influenced by the cytokine milieu within the tumor environment; IFNγ and TNFα promote an M1 phenotype, while TGFβ encourages the M2 phenotype." (PMID 38594256, 2024). "On the other hand, in cancer resistant to TNFα-induced cytotoxicity, TNFα has the capacity to incite proliferation, enhance cancer cell survival, promote migration, and stimulate angiogenesis, resulting in tumor promotion." (PMID 39204319, 2024). "This implies that PANoptosis caused by synergism of TNF-α and IFN-γ, among other immune cell cytokines, is an important mechanism to kill cancer cells and suppress tumor growth, presenting a potential therapeutic target." (PMID 38169587, 2024). "The M1 - polarized TAMs secrete pro - inflammatory cytokines such as TNF - α and IL - 12, which enhance the anti - tumor immune response." (PMID 39712021, 2024). "Infiltration of immune cells, such as macrophages, into tumoral regions results in the release of proinflammatory cytokines (IL-6; IL-17; TNF-α), fostering tumor proliferation, survival, and invasion." (PMID 38892375, 2024). "Shark cartilage extracts have been shown to disrupt tumor necrosis factor-α(TNFα) and basic fibroblast growth factor (bFGF)-induced angiogenesis and to prevent the growth of various tumor cells." (PMID 39061775, 2024). "This enhances the infiltration of effector T cells (CD4+ and CD8+ T cells) into the tumor, promoting the release of pro-inflammatory cytokines (TNF-α, IL-6, and IL-12), killing the cancer and reversing tumor resistance." (PMID 39004737, 2024). "IL-21 regulates the function of CD8+ T cells through the tumor necrosis factor-α (TNF-α)/IL-17 pathway, mediating tumor regression." (PMID 39534095, 2024). "This activation, in turn, triggers the secretion of cytokines such as IL-6 and TNFα, supporting the proliferation of tumor cells and formation of lung metastases." (PMID 38331871, 2024).
tumor (continued). "IFN-γ and TNF-α are biological factors capable of eliminating numerous tumor cells and activate other lymphocytes, such as T and B lymphocytes." (PMID 38434708, 2024). "M1 can activate cytotoxic T lymphocytes through antigen presentation and secrete pro-inflammatory cytokines such as TNF-α to impede tumor development." (PMID 39497925, 2024). "More functional CD8+ T cells that were tumor-specific (eGFP tet+) or expressed IFN-γ or TNF-α were observed in Gsdmc-WT tumors." (PMID 37883181, 2024). "This treatment also increased the infiltration of CD8+ T cells and macrophages, as well as the mRNA expression levels of IL-12, IFN-γ, IL-2, IL-10, TNF-α, and PD-L1 in the tumor microenvironment." (PMID 39367471, 2024). "Interleukin 6 (IL‐6) and tumor necrosis factor α (TNF‐α) were positively correlated numbers of tumor cells, indicating that the amount of CpG release was dependent on the number of tumor cells." (PMID 38145350, 2024). "In cellular experiments, PRMT1 also upregulated H4R3me2a to induce tumor cell proliferation and promote tumor cell metastasis via the tumor necrosis factor signaling pathway." (PMID 39619442, 2024). "TNF cascade promotes tumor invasion and migration, while a high neutrophil-to-lymphocyte ratio increases mortality." (PMID 38339347, 2024). "Data from the literature indicate that TNF-α can trigger the activation of pathways related to the inhibition of tumor growth, including signaling via the NF-κB and MAPK pathways." (PMID 39000182, 2024). "In tumor cells, this membrane-bound form of TNF-α has been found to regulate cell survival depending on the direction of the signal." (PMID 38625986, 2024). "Recent studies have highlighted the significant roles of cytokines such as IL-10, IL-17, and TNF-α in immune regulation and tumor progression." (PMID 39456637, 2024). "Neural-like tumor cells had the strongest expression of TNF and MYC signaling, and intermediate cells had the strongest interferon signaling." (PMID 39417106, 2024). "M1 inhibits tumor growth through the synthesis of proinflammatory cytokines, such as tumor necrosis factor-α (TNF-α), IL-1, IL6, IL-12, IL-23, and reactive nitrogen and intermediate oxygen compounds, thus ensuring the phagocytosis of defective cells." (PMID 39201801, 2024). "Research shows that frailty can lead to elevated levels of IL-6, C-reactive protein (CRP), and TNF-α in the tumor microenvironment." (PMID 39042180, 2024). "Tumor-derived TNF-α induces PD-L1 expression on mast cells through activating the NF-κB pathway, thus inhibiting T cell immunity and gastric cancer progression." (PMID 38762484, 2024). "The reduction of oxidative stress through the inhibition of TNF-α signaling in tumor cells or through the scavenging of reactive oxygen species (ROS) antagonized the therapeutic effects of immunotherapy." (PMID 39650654, 2024). "The discovery of TNF originated from the observation that cancer patients occasionally exhibited spontaneous tumor regression following bacterial infection." (PMID 38835752, 2024). "Research indicates that TGF-β can suppress the activity of M1 macrophages, the main components exerting anti-tumor immune responses among macrophages, through the Smad7 and TNF pathways." (PMID 38767747, 2024). "Activated Th cells also release a variety of factors, such as IL-6, IL-11, IL-15, RANKL, and TNF-α, which promote osteoclastogenesis and bone resorption and provide a favorable environment for tumor bone metastasis." (PMID 38464516, 2024). "This involves the activation of genes that encode pro-inflammatory cytokines like tumor necrosis factor-alpha (TNF-α) and interleukin-6 (IL-6), which not only sustain inflammatory responses but also support tumor growth and survival." (PMID 38474160, 2024). "Increased accumulation of TNF-α producing CD4+ Th cells in the tumor microenvironment was also observed in mice after treatment." (PMID 38920557, 2024).
tumor (continued). "The tumor immune microenvironment (TME) includes immune cells, cytokines like IL-6 and TNF-α, and regulatory factors, all of which contribute to tumor progression and metastasis." (PMID 39896817, 2024). "In contrast, TNF expression negatively correlated with tumor size (r= -0.18, P = 0.040) and tumor volume (r= -0.18, P = 0.040)." (PMID 38965454, 2024). "Activated CD8+ T cells secrete IFN-γ and TNF-α, initiating a cascade of inhibitory immune responses against the tumor." (PMID 38352877, 2024). "TNF-α also plays a role in the killing of tumour cells by natural killer cells and CD8+ lymphocytes." (PMID 39046819, 2024). "Tumor cells can release large amounts of pro-inflammatory cytokines, including TNF-α, IL-6, and IL-1β, into the bloodstream." (PMID 39697630, 2024). "Another secreted product, TNF-α, despite its potential derivation from various immune cells, undeniably plays a role in inducing the rupture of tumor blood vessels, promoting cell infiltration, and maintaining an ischemic state in tumors." (PMID 38840908, 2024). "Specifically, TNF-α modulates tumor development, invasion, metastasis, acquired drug resistance and the induction of adaptive and innate immune responses." (PMID 38341519, 2024). "The combined knockdown of BCL3 and TNFα blocked this increase, suggesting the ‘tumour initiating phenotype” of suppressed BCL3 was mediated by TNFα." (PMID 38195591, 2024). "In one of the experimental studies, Phytolacca acinosa polysaccharides I (PAP-I) was studied for the anti-tumor activities and their effects on the tumor necrosis factor (TNF) induction and peritoneal macrophage’s immunological cytotoxicity." (PMID 39850573, 2024). "The endurance exercise induced a reprogramming of M2 macrophages in M1 type, as witnessed by a reduction in the expression of CD86, Tumor necrosis factor (TNF)- α and nitric oxide synthase (iNOS) markers, delaying tumor growth." (PMID 39555455, 2024). "M1 macrophages produce various pro-inflammatory mediators, including TNF-α, IL-1, IL-6, active nitrogen and oxygen intermediates, which exhibit potent bactericidal and tumor-killing activities, give aid to infection clearance and trigger inflammation." (PMID 38715602, 2024). "M1 macrophages and natural killer cells, for instance, can eliminate tumor cells and foster their senescence through the secretion of IFN-γ and TNF-α, thereby restraining tumor expansion." (PMID 39267750, 2024). "Th1 cells released TNF-α, which then stimulated neutrophil recruitment, finally playing an inhibitory role in tumor growth." (PMID 39252305, 2024). "CD8+ T cells kill tumor cells by releasing granules containing perforin and granzyme or by cytokines such as TNF‐alpha and IFN‐gamma." (PMID 38572921, 2024). "TNF-α was first identified as a factor that promotes tumor necrosis, but it has lately been discovered to have additional significant activities." (PMID 38792366, 2024). "Myeloid cells, including monocytes, macrophage and DCs, are the main cellular sources of TNFα, and macrophages are the most abundant support cell in the tumor microenvironment." (PMID 39105847, 2024). "A significant association between omega-3 fatty acids and muscle inflammation is established through the down-regulation of pro-inflammatory cytokines such as tumor TNF-α) and IL-6, as well as the reduction in ROS production." (PMID 39770885, 2024). "Functional analyses of the non-Vδ1Vδ2 cells revealed that they had a much lower expression of IFN-γ and TNF than Vδ2 cells, suggesting a lower capacity to support anti-tumour immunity." (PMID 38953978, 2024). "On the one hand, research has demonstrated that TNF-α promotes tumor growth by enhancing proliferation, survival, and angiogenesis in cancer cells that are resistant to its cytotoxic effects." (PMID 39411143, 2024).
tumor (continued). "CD4 + helper T (Th) cells role in anti-tumor immune responses is mediated by the secretion of several cytokines, such as tumor necrosis factor (TNF) and interferon-γ (IFN-γ), which activate macrophages and improve CD8 + T cell responses." (PMID 37721693, 2024). "On the one hand, MCs are also a source of a variety of cytokines, including IL-1, IL-4, IL-8, IL-6, MCP-3, MCP-4, and TNF-α, which contribute to the inhibition of tumor development." (PMID 39126091, 2024). "As a result of the studies, it has been observed that TNF-α, which increases tumor growth and migration, exhibits anti-tumoral effects through the high local application." (PMID 39175950, 2024). "Upon evaluation of the efficacy of the combination therapies, M-NP addition to the treatment program produced a strong elevation in the levels of IL-10 and TNF-α indicating activation of a powerful systemic anti-tumor immune response." (PMID 37612575, 2024). "A significant (P < 0.05) difference was also observed in tumor-free mice when treated with WFA compared in tumor-free mice treated with vehicle suggesting beneficial effect of WFA on down regulation TNFα in kidney." (PMID 39394174, 2024). "They found that mice treated with PA-MSHA had higher levels of effector T cells and pro-inflammatory cytokines, such as IFN-γ and TNF-α, which have an anti-tumor effect." (PMID 38339275, 2024). "CLL cells and tumor-associated stromal cells also produce and secrete FGF-2, TNF-α, CXCL-12, CXCL-2, NGAL, IGF-1, progranulin, and angiogenin." (PMID 39796700, 2024). "It exhibits dual functionality: on one side, TNF-α acts as an endogenous tumor promoter by stimulating cancer cell growth, proliferation, invasion, metastasis, and tumor angiogenesis." (PMID 39605908, 2024). "TNF-alpha, a pro-inflammatory cytokine, is designed to destroy tumor cells by activating protein transcription upon binding to its receptors." (PMID 39337983, 2024). "In the body, quercetin reduces the effects of inflammatory mediators and cytokines such as TNF-α, IL-6, thus exerting anti-inflammatory and anti-tumor effects." (PMID 39193369, 2024). "Tumor-induced cytokines such as TNF-α, interleukin 1 beta, and IL-6 contribute to the inhibition of albumin gene expression in cachexia." (PMID 38339365, 2024). "Activated YAP1 upregulates the secretion of IL-6 and TNF-α from tumor cells, as well as colony-stimulating factor 1-3 (CSF1-3), CXC motif chemokine ligand 5(CXCL5), PGE2, COX2, and other factors that recruit MDSCs." (PMID 38550587, 2024). "By studying the interrelationship between tumor cells and immune cells, we found that OS cells affect IL1β+ macrophages through the TNF signaling pathway." (PMID 39767767, 2024). "This autocrine activity of TIMP-1 positions it alongside other key immunomodulatory cytokines such as IFN-γ and TNF-α, known for their efficacy in tumor immunity." (PMID 38777826, 2024). "The recruitment and activation of neutrophils, macrophages, and lymphocytes at sites of damage, infection, and tumor development is a result of TNF-α and other proinflammatory factors." (PMID 38231411, 2024). "Pro-inflammatory cytokines like IL-6 and TNF-α can promote tumor cell proliferation and survival, while anti-inflammatory cytokines such as IL-10 contribute to immune evasion." (PMID 39200315, 2024). "In fact, TNF-α signaling via NF-κB was the top positive enrichment from RNA-Seq of post-enzalutamide tumor samples." (PMID 39560993, 2024). "Some microorganisms would promote the recruitment and activation of CD8 T cells, increase IFN-γ, TNF-α and IL-2 in serum, and promote the anti-tumor immune response." (PMID 39034996, 2024).
tumor (continued). "Consistent with the cytotoxic potential of UniCAR T-cells obtained, the secretion of Interferon gamma (IFNγ), Interleukin 2 (IL-2) and Tumor Necrosis Factor alpha (TNFα) increase in a TM dose-dependent manner in both FAP+ tumor models and for all TMs." (PMID 39000348, 2024). "In murine systems, the requirement of IFNγ for tumor Nos2 expression has been shown, which was amplified by other cytokines including IL1β and TNFα." (PMID 39356141, 2024). "Tumor necrosis factor-α (TNF-α) is a cytokine that plays a complex role (pro-inflammatory and anti-tumor) in cancer patients." (PMID 39246660, 2024). "On the other hand, TNF-α can also promote tumor angiogenesis by inducing infiltration of macrophages and neutrophils expressing COX-2." (PMID 38892375, 2024). "TNFα+ myeloid cells, especially pro-inflammatory macrophages, can induce tumor cell death and immune response within the tumor, and IL-12+ myeloid cells can stimulate IFN-α producing CD8+ T and NK cells." (PMID 39702544, 2024). "The typical molecular inflammatory signature in the tumor microenvironment includes both proinflammatory cytokine (IL-1, TNF-α, IL-6, and IL-8) and chemokines (CCL20, CXCL13, and CXCL8)." (PMID 38256080, 2024). "Since its identification in 1975, TNF has been extensively studied due to its pleiotropic functions including anti-tumor activity." (PMID 39615678, 2024). "TAMs enhance their own AMPK and peroxisome proliferator-activated receptor-gamma coactivator 1α (PPARγC1α) to promote tumor hypoxia while releasing TNF-α to boost glycolysis in tumor cells." (PMID 39430253, 2024). "CD4+ T cells alter tumor metabolism leading to enhanced TNF-α-dependent oxidative stress and tumor cell death." (PMID 39068665, 2024). "IL-10 has been associated with inhibiting neovascularization and tumor metastasis by downregulating the synthesis of VEGF, IL-1β, TNF-α, IL-6, and MMP-9 in tumor-associated macrophages and natural killer (NK) cell-dependent mechanisms, respectively." (PMID 38672182, 2024). "In a syngeneic mouse melanoma experiment, the bacteria induced the upregulation of TNF-α, resulting in a synergistic effect with the secreted immunotoxin and significantly inhibiting tumor growth." (PMID 38654309, 2024). "Escherichia coli strain Nissle 1917 (EcN) has been identified as a positive regulator of TNF-α in tumor infiltrating lymphocytes (TILs), leading to the inhibition of tumor growth." (PMID 38835386, 2024). "Meanwhile, it can also recruit MDSCs (myeloid-derived suppressor cells) by activating NF-κB pathway, which promotes the secretion of IL-6 and TNF-α to induce tumor proliferation." (PMID 38444674, 2024). "In a preclinical study, an adenovirus encoding tumor necrosis factor-α and interleukin-2 was found that induce the formation of TLS, enhance ICB efficacy, inhibit tumor growth, and prolong survival in head and neck tumor-bearing mice." (PMID 38583352, 2024). "Initially recognized for its ability to induce rapid hemorrhagic necrosis in experimental cancers, TNFα has demonstrated a paradoxical role in promoting tumors as endeavors to exploit its anti-tumor activity progressed." (PMID 38610706, 2024). "It activates key signaling pathways such as PI3K/Akt and NF-κB and stimulates proinflammatory cytokines like TNF-α and IL-6, facilitating tumor growth, angiogenesis, and metastasis." (PMID 39184804, 2024). "In cancers, TNF-α plays a dual role, promoting tumor cell survival and proliferation in low doses while inducing cell death in higher concentrations through NF-κB activation." (PMID 39766123, 2024). "Tumor necrosis factor-alpha (TNFα) from T cells and NK cells is also stimulated to reduce IL-4-mediated suppression of IFNγ and upregulate tumor cell MHC I and II expression for enhanced recognition and lysis." (PMID 39697343, 2024).